FGF21 (fibroblast growth factor 21)
Diseases named in the same sentence as FGF21 in open-access papers (continued):
Sharing a sentence is not in itself a finding about the gene and the disease.
Hepatic steatosis (continued). "The administration of doses of 5 × 1010 vg/mouse or higher of FGF21‐encoding vectors completely prevented the development of hepatic steatosis, which correlated with the weight of the organ and its total triglyceride and cholesterol content." (PMID 29987000, 2018). "In pediatric intestinal failure, an increase in FGF21 in the serum is significantly associated with hepatic steatosis, and correlated with the duration of IV nutritional support." (PMID 28118819, 2017). "Several studies demonstrated that serum FGF-21 concentrations were associated with hepatic fat content especially in subjects with moderate hepatic steatosis." (PMID 28326329, 2017). "Conversely, fibroblast growth factor 21 (FGF-21), a hormone exists in liver and fat, dose dependently reduces body weight and hepatic steatosis is largely associated with inhibition of nuclear SREBP-1." (PMID 26843619, 2016). "FGF21 production was impaired in CREBH-deficient mice, and adenoviral overexpression of FGF21 suppressed adipose tissue lipolysis and improved hepatic steatosis in these mice." (PMID 27301791, 2016). "In the current study, we demonstrated that loss of CREBH decreased FGF21 production from the liver, increased adipose tissue lipolysis and worsened hepatic steatosis, which was partially reversed by adenoviral overexpression of FGF21." (PMID 27301791, 2016). "UA significantly up-regulates the expression of miR-149-5p in hepatocytes, and FGF21, a downstream target of miR-149-5p and closely related to lipid metabolism, whose deficiency can lead to hepatic steatosis, so that uric acid aggravated hepatic fat accumulation through the miR-149-5p/FGF21 axis." (PMID 39669496, 2024). "Moreover, induction of FGF21 in response to protein restriction appears to be required for the associated reduction in hepatic steatosis." (PMID 39136056, 2024). "Additionally, considering that impaired adaptive thermogenesis is related to an elevated susceptibility to hepatic steatosis, we examined alterations in the expression of a crucial regulator of the thermogenic program, FGF21, in the liver." (PMID 39408777, 2024). "To uncover the mechanisms underlying the improvement in hepatic steatosis by a KD, we performed RNA-Seq analysis on mouse livers and found that the mRNA expression profile of Fgf21 signaling was significantly upregulated, especially Fgf21, Klb, and Fgfr1." (PMID 38609395, 2024). "Taken together, the underlying mechanisms of 20E to mitigate hepatic steatosis may also involve the activation of FGF21, which contributes to the suppression of DNL via AMPK and ACC pathway." (PMID 37509710, 2023). "Furthermore, alcohol-induced hepatic steatosis has been associated with the release of FGF21 (Fibroblast Growth Factor 21) in the plasma." (PMID 38067261, 2023). "Despite the very modest impact of GDF15 and FGF21 ‘loss-of-function’ on body weight, they remain of considerable interest as pharmacological ‘gain-of-function’ targets in relation to their impact on body weight and on hepatic steatosis." (PMID 36064109, 2022). "Of note, PPARα- or FGF21- deficient mice fed the MCD diet were more prone to hepatic steatosis." (PMID 35269812, 2022). "In addition, several studies have reported that FGF21 overexpression influences weight loss and hepatic steatosis." (PMID 36077368, 2022). "FGF21 is known to increase energy expenditure, fat utilization, and lipid excretion, causing weight loss, increased insulin sensitivity, decreased blood glucose and lipid levels, and the amelioration of hepatic steatosis." (PMID 36516179, 2022). "Therefore, we focused on the role of FGF21 in preventing diet-induced hepatic steatosis in Ahnak-deficient mice." (PMID 33785868, 2021). "However, recent studies reported different results that deficient of FGF21 induced hepatic steatosis, and overexpression of FGF21 was able to ameliorate liver fat accumulation." (PMID 32070295, 2020).
Hepatic steatosis (continued). "Ovariectomized female rats had reduced hepatic expression of FGF21, increased hepatic steatosis and a greater accumulation of liver fat compared with non‐ovariectomized female rats, and oestrogen replacement was associated with reduced hepatic steatosis and increased FGF21 expression." (PMID 31687174, 2019). "In this study, we demonstrated that γ-GT, FGF-21, TG, and BMI were significantly associated with liver steatosis severity in obese and overweight children and may be used as the initial assessment." (PMID 31750276, 2019). "Further studies to explore serial samples of FGF-21 levels and the association with histology of fatty liver disease severity and longitudinal outcome may increase the significance of these findings." (PMID 31750276, 2019). "The increase of FGF21 expression by CO is associated with alleviating metabolic disorders, including improving glucose tolerance and insulin sensitivity and in ameliorating hepatic steatosis and adipose tissue dysfunction." (PMID 29295856, 2018). "FGF21 depletion exacerbated alcohol-induced hepatic steatosis and liver injury, which was associated with increased activation of genes involved in lipogenesis mediated by SREBP1c and decreased expression of genes involved in fatty acid β-oxidation mediated by PGC1α." (PMID 27498701, 2016). "Although FGF-21 has beneficial effects on lipid metabolism and is protective against hepatic steatosis, fatty liver has been associated with elevated FGF-21, possibly either as compensation for increased hepatic steatosis, or because fatty liver is associated with FGF-21 resistance." (PMID 27182456, 2016). "Given that prolonged fasting also induces hepatic steatosis, it is tempting to speculate that the TG accumulation underlies FGF21 expression in fasted mice." (PMID 27301791, 2016). "Fibroblast growth factor 21 reduced lipid levels and reversed hepatic steatosis, which was associated with FGF21 inhibition of nuclear sterol regulatory element binding protein-1 and the expression of a wide array of genes involved in fatty acid and triglyceride synthesis." (PMID 24373582, 2014). "In the present study, we demonstrated the close association of serum FGF21 concentrations with intrahepatic fat content in 138 patients with abnormal glucose metabolism and with B ultrasound-diagnosed hepatic steatosis, whose hepatic fat content were distributed in a large range (2.47%–81.95%)." (PMID 21949781, 2011). "Elevating serum FGF21 levels through exogenous administration or liver overexpression induces weight loss, enhances energy expenditure, improves glucose metabolism and insulin sensitivity, alleviates hepatic steatosis, promotes lipolysis, induces browning of WAT, and activates BAT function." (PMID 38609395, 2024). "Another study was done in order to discover the association between genetic variations of FGF21 and Metabolic Associated Fatty liver diseases (MAFLDs) suggesting that rs838136 could be a risk factor for MAFLDs via changes in folding and stability of FGF21 mRNA." (PMID 36457562, 2022). "In addition, high serum levels of FGF21 are associated with hepatic steatosis." (PMID 26441837, 2015). "Overall, PAC alleviates hepatic steatosis in NAFLD by enhancing FGF21 expression, activating the FGF21/FGFR1 signaling axis, and inhibiting p38MAPK activation." (PMID 42100018, 2026). "To confirm the mechanistic role of PAC in hepatic steatosis, we inhibited FGF21 expression in HepG2 cells using nAbFGF21." (PMID 42100018, 2026). "Conversely, FGF21 overexpression, or treatment with FGF21, improves insulin sensitivity, reduces hepatic steatosis, increases thermogenic capacity of white and brown adipose tissues, and improves β-cell function." (PMID 40604130, 2025). "It identifies hepatic steatosis as the key driver of metabolic dysfunction, mediated by FGF21 resistance and bile acid dysregulation." (PMID 41438464, 2025).
Hepatic steatosis (continued). "In this research, we evaluated the performance of a commercial ELISA kit for FGF21 measurement and investigated its potential as a blood-based biomarker for the diagnosis of hepatic steatosis." (PMID 40563517, 2025). "FGF21 and its analogues increase insulin sensitivity, reduce hepatic steatosis, and have antifibrotic activity, and thus are excellent drug candidates in MASLD." (PMID 41356370, 2025). "FGF21 knockout mice develop significant hepatic steatosis in response to ketogenic, and amino acid-deprived diets through impaired fatty acid oxidation and increased lipogenesis." (PMID 40604130, 2025). "Induction of Fgf21 in adipose tissue contributes to alcohol-induced lipolysis and exacerbates hepatic steatosis." (PMID 40381698, 2025). "FGF21 administration and diet reversal improved liver steatosis and inflammation almost to the point of complete resolution; in particular, diet reversal reduced fibrosis." (PMID 40496439, 2025). "Some authors have shown higher FGF-21 concentrations in more severe hepatic steatosis, inflammation, or fibrosis." (PMID 40430125, 2025). "Ketogenic diets enhance hepatic FGF-21 signaling, improving hepatic steatosis by promoting fatty acid oxidation and inhibiting lipogenesis." (PMID 40437610, 2025). "SGLT2 inhibitors, known for improving hepatic steatosis and fibrosis, have been reported to induce these beneficial effects through the enhancement of FGF-21 activity." (PMID 40937171, 2025). "In HFD-fed IR mice, WAT-specific overexpression of Fgf21 improved metabolic function by reducing inflammation, IR, and hepatic steatosis." (PMID 40855499, 2025). "Our findings indicate that between 2014 and 2018, the focus was on regulating the expression of fibroblast growth factor 21 (FGF21) through experimental gene editing in mice for the treatment of fatty liver." (PMID 41502820, 2025). "For the diagnosis of steatotic liver (with an attenuation coefficient cut-off of 0.66), ROC curve analysis demonstrated an AUC of 0.727 for plasma FGF21 in detecting hepatic steatosis." (PMID 40563517, 2025). "Further, serum FGF-21 levels were associated with MAFLD and increased significantly and gradually in parallel with hepatic steatosis scores." (PMID 40430125, 2025). "This study validates the analytical and clinical performance of a commercial FGF21 ELISA kit for assessing hepatic steatosis." (PMID 40563517, 2025). "Studies have shown that FGF21 gene therapy reduces body weight, adipose tissue hypertrophy and inflammation, and hepatic steatosis, and improves insulin sensitivity, with sustained effects present for over 1 year in obese mice." (PMID 40663389, 2025). "FGF21 knockout mice on a high-fat diet exhibit a worsening of metabolic liver injury, hepatic steatosis, and MASH-HCC transition." (PMID 40604130, 2025). "FGF21/sTGFBR2 or FGF21 alone was sufficient to reduce hepatic steatosis in lipodystrophic mice, and dual FGF21/sTGFBR2 therapy reduced cortical bone volume fraction." (PMID 40663389, 2025). "Third, hepatic steatosis in MAFLD can damage mitochondrial function and hepatic peroxisomes, causing the reduced release of fibroblast growth factor 21 (Fgf21)." (PMID 40607218, 2025). "Diagnostic performance indicated 84% sensitivity and 81% specificity at defined FGF21 thresholds for the diagnosis of hepatic steatosis." (PMID 40563517, 2025). "Liver FGF21-KLB signaling plays a critical role in the KD-induced amelioration of hepatic steatosis." (PMID 38609395, 2024). "B1344 is a long-acting PEGylated FGF21 analog that significantly reduced hepatic steatosis, inflammation, and fibrosis in cynomolgus monkeys with MASLD undergoing liver biopsies." (PMID 38891828, 2024). "By elucidating the crucial involvement of the FGF21-KLB pathway in KD’s beneficial effects on hepatic steatosis, this study sheds light on the intricate interplay among dietary interventions, metabolic signaling pathways, and hepatic lipid metabolism." (PMID 38609395, 2024).
Hepatic steatosis (continued). "In nonalcoholic fatty liver disease, hepatic steatosis and inflammation led to reduced FGF21 levels due to NF-κB-mediated Fgf21 transcription or interaction with SREBP1c with FGF21." (PMID 39766329, 2024). "Although FGF21 can be induced by oxidative stress and be activated in obese mice and in NASH patients, elevated FGF21 paradoxically protects against oxidative stress and reduces hepatic steatosis." (PMID 39436790, 2024). "The activation of FGF21/AMPK/PGC-1α signaling pathway in the liver plays a crucial role in suppressing hepatic steatosis and protecting mitochondrial function." (PMID 39161898, 2024). "This study aims to delve deeper into the influence of KD on FGF21 expression and its responsiveness through the FGF21-KLB pathway, underscoring the pivotal role of FGF21-KLB signaling in mediating the KD’s beneficial effects on hepatic steatosis." (PMID 38609395, 2024). "This study aimed to delineate the critical role of FGF21 signaling in the ameliorative effects of KD on hepatic steatosis." (PMID 38609395, 2024). "Through cell transfection and analysis, we observed that chimeric FGF21/HGFR has the effect of regenerating normal hepatocellular properties in non-alcoholic fatty liver." (PMID 38542065, 2024). "In this study, we aimed to delineate the critical role of FGF21 signaling in the ameliorative effects of KD on hepatic steatosis in order to offer new insights into the potential of KD in the treatment of NAFLD." (PMID 38609395, 2024). "In animal models, the administration of FGF19 and FGF21 improves insulin sensitivity, lipid levels, and liver steatosis while ameliorating body weight and fat mass." (PMID 38891828, 2024). "Most importantly, however, clinical and mouse studies have reported increased plasma FGF21 concentration in patients and animal models of MASLD, and thus FGF21 has been proposed as a marker of liver steatosis." (PMID 38587078, 2024). "Since plasma levels of FGF21 are thought to reflect the severity of hepatic steatosis, this result suggests that KO male mice suffer from a more severe state of liver damage." (PMID 38519536, 2024). "Our studies identify SIRT1 as an endogenous regulator of the fibroblast growth factor 21 (FGF21) hepatocyte‐derived hormone FGF21 which reduces hepatic steatosis and increases energy expenditure in young mice." (PMID 36999514, 2023). "It has been shown that FGF21 stimulates lipolysis by decreasing fat stores leading to reducing hepatic steatosis and lipotoxicity." (PMID 37347041, 2023). "In mouse models, the overexpression of hepatocyte-specific FGF21 can ameliorate HFD-induced liver steatosis." (PMID 36594101, 2023). "Fibroblast growth factor 21 (FGF21) protects against high-fat high-cholesterol diet (HFCD)-induced hepatic steatosis, inflammation, and fibrosis." (PMID 36648330, 2023). "FGF21 transgenic mice exhibited enhanced insulin sensitivity, reduced hepatic steatosis, and increased BAT mass." (PMID 37432218, 2023). "It has been found to reduce fatty liver disease and steatohepatitis, a disorder of lipid metabolism in non-alcoholic fatty liver disease mice, through upward regulation of the FGF21/FGFR1 pathway." (PMID 37958806, 2023). "We observed that recombinant FGF21 improved hepatic steatosis and HIO in the PCB-induced NAFLD/NASH models." (PMID 36012166, 2022). "Subsequently, we investigated the effect of recombinant FGF21 on hepatic steatosis in the PCB-induced NAFLD/NASH models." (PMID 36012166, 2022). "FGF-21 analogues have been shown to significantly reduce the amount of hepatic steatosis in NASH patients in clinical trials." (PMID 35204498, 2022). "In preclinical studies, FGF21 administration reduced hepatic steatosis and inflammation in different NASH models." (PMID 36012166, 2022). "Dealing with junk foods such as potato chips, candy and soft drinks, an intriguing mechanism linking alcohol abuse, junk food and hepatic steatosis has recently been proposed, focusing on fibroblast growth factor 21 (FGF21)." (PMID 36142317, 2022).
Hepatic steatosis (continued). "In contrast, FGF21 null mice gained weight and developed obvious hepatic steatosis after ketogenic diet ingestion." (PMID 36618930, 2022). "FGF21 pharmacological treatment reverses fatty liver and lowers serum triglyceride concentration but FGF21 serum level is increased in hepatic steatosis." (PMID 35909532, 2022). "In this study, we report the benefit of FGF21 treatment for improving hepatic steatosis depends on sex." (PMID 35998055, 2022). "Treatment with FGF21 has been shown to improve glucose and lipid homeostasis, ameliorate hepatic steatosis, preserve β-cell functions, increase the number of brown adipocytes, and decrease atherosclerosis." (PMID 35323680, 2022). "It had been shown previously that exogenous administration of FGF21 significantly lowers circulating and intrahepatic triglycerides, reverses fatty liver, and reduces signs of NASH and hepatic fibrosis." (PMID 35909532, 2022). "It has been reported that vitamin C ameliorates perfluorooctane sulfonate-induced hepatic steatosis and elevates FGF21 levels in circulation." (PMID 36434042, 2022). "In a meta-analysis, FGF-21 was found to be a potential biomarker for liver steatosis and its progression to steatohepatitis, but it had low sensitivity and specificity, i.e., 0.62 and 0.78, respectively." (PMID 35204498, 2022). "Studies have shown that FGF21 deficiency leads to glucose metabolism dysfunction as well as IR in mice, and exogenous FGF21 intake attenuates hepatic steatosis in mice." (PMID 36397950, 2022). "Early studies with a fibroblast growth factor 21 agonist have shown to reduce plasma triglycerides and hepatic steatosis and improve glucose homeostasis." (PMID 35107764, 2022). "Long-acting FGF21 partially affects the FGF21-adiponectin-IL17A pathway to reduce liver steatosis and inflammation in the NASH mouse model." (PMID 36267567, 2022). "In summary, the present study suggests that FGF21 administration can ameliorate fatty liver diseases and HCC furthermore studies are needed." (PMID 36457562, 2022). "Based on this, the plasma FGF21 concentration has even been suggested as a surrogate marker for fatty liver in humans." (PMID 34517929, 2021). "Administration of FGF21 can reduce hepatic TG accumulation and thus reverse body weight gain and hepatic steatosis in rodents and primates." (PMID 33785868, 2021). "Deleting FGF21 from LSD1-LKO liver partially reversed the improved hepatic steatosis, likely due to the FGF21-dependent alteration of lipid uptake (Cd36) and secretion (ApoB, ApoA4, and ApoA5)." (PMID 34314389, 2021). "Sex differences exist in the prevalence, risk factors, fibrosis, and clinical outcomes of NAFLD, and our results highlight the need for preclinical testing of FGF21 actions on liver steatosis, not only in males, but also in females." (PMID 34943946, 2021). "Some studies found that administration of FGF21, FGF21 analogs, or adenoviral delivery of FGF21 will reduce hepatic steatosis in diverse rodent models of NAFLD." (PMID 33869312, 2021). "Although the underlying mechanism whereby GDF15 protects against hepatic steatosis is unclear, our data suggest that GDF15 and FGF21 have differing roles in liver fat homeostasis." (PMID 33718833, 2021). "Collectively, we have shown in our study that the deletion of Camp protects mice against HFDE-induced liver steatosis, injury and inflammation through upregulating FGF21/adiponectin signaling and increasing adipose lipolysis in the eWAT." (PMID 34943840, 2021). "The results showed higher plasma FGF-21 levels in obese youth, especially in those with fatty liver, independently from BMI, visceral fat, and insulin sensitivity." (PMID 33889132, 2021). "Lipid homeostasis and hepatic steatosis in DIO mice in the FGF21 treatment group were significantly improved." (PMID 33869312, 2021). "Treatment with FGF21 can reduce hepatic TG accumulation and hepatic steatosis, thus attenuating body weight gain in rodents and primates." (PMID 33785868, 2021).